RNU4-22P (RNA, U4 small nuclear 22, pseudogene)
Gene: Small nuclear RNA gene on chromosome 14 (88,513,498 to 88,513,663, forward strand). Ensembl gene ENSG00000222990.
Homologues: Orthologues: chimpanzee U4 (99% identical), macaque U4 (61% identical), rat LOC120097638 (46% identical), tropical clawed frog U4 (43% identical), dog U4 (40% identical), rabbit U4 (39% identical), mouse Gm25102 (37% identical). Paralogues in human: RNU4-82P (50% identical), RNU4-25P (49% identical), RNU4-84P (46% identical), RNU4-15P (45% identical), RNU4-74P (45% identical), RNU4-48P (44% identical), RNU4-5P (44% identical), RNU4-64P (44% identical), RNU4-21P (43% identical), RNU4-39P (43% identical), RNU4-57P (43% identical), RNU4-91P (43% identical), and 80 more.